DCC (DCC netrin 1 receptor)
Diseases named in the same sentence as DCC in open-access papers (continued):
Sharing a sentence is not in itself a finding about the gene and the disease.
tumor (continued). "Regarding therapeutic opportunities, it is admitted that Netrin‐1 promotes tumor cell survival (Unc‐5 Netrin Receptor B) through interactions with receptors such as DCC and UNC5." (PMID 40235169, 2025). "Given DCC’s tumor-suppressive function, blocking Netrin-1/DCC interactions has emerged as a potential therapeutic approach to disrupting prosurvival signaling in cancer cells." (PMID 40243726, 2025). "Some are tumor suppressor genes, such as Phosphatase and Tensin Homolog (PTEN) and Deleted in Colorectal Cancer (DCC), which are very low expressed in CRC, and their mutation and inactivation can stimulate tumor growth." (PMID 38315263, 2024). "Multiple tumor driver genes that are associated with spermatogenesis pathway such as mTOR, EZH2, NF2, DCC and MLF1 had high enrichment score in the EGFR group." (PMID 35428753, 2022). "Immunoblotting of transplanted tumor tissues from BALB/C-nude mice indicated that DCC-2036 significantly inhibited p-AXL, AXL, and KLF5." (PMID 36042208, 2022). "In intestinal cancer, DCC suppresses tumor growth by inducing cancer cell death when netrin-1 expression is low." (PMID 36499024, 2022). "DCC is another chromosome 18 gene with well-established tumor suppressor activity in other tumor types." (PMID 34680217, 2021). "While the tumor suppressors DCC and SMAD4 have been nominated as possible drivers of this event through haploinsufficiency, more work is needed to fully understand the role of chr18 loss in SI-NET30,31." (PMID 34737276, 2021). "In these tumors, the gain of netrin-1 or the deletion of Unc5b and DCC prevents tumor cells from undergoing apoptosis and thereby promotes tumor growth and metastases." (PMID 35008701, 2021). "DCC expression is lowered in small intestinal NETs, consistent with a tumor suppressive role in these tumors." (PMID 34680217, 2021). "DCC is relatively abundant in fully differentiated cells but declines in the early stages of carcinogenesis, falling further with advancing tumor stage and reduced patient survival." (PMID 32117748, 2020). "Despite the lack of identifiable recurrent mutations specific to either primary or metastatic tumours, single subclonal mutations in CITTA (OVA_048), DCC (OVA_048) and FAT1 (OVA_048) were all specific to primary tumours." (PMID 32099096, 2020). "NEO1 and DCC are also tumor suppressors that can inhibit metastasis by acting as dependence receptors." (PMID 30858446, 2019). "DCC functions as a tumor suppressor in a various types including malignant astrocytomas where its reduced expression correlates with unfavorable prognosis." (PMID 31083655, 2019). "Tumor treatment with DCC-2701 was able to efficiently reduce the tumor burden in vivo by inhibition of c-Met phosphorylation and c-Met-mediated signaling, for cell growth and migration." (PMID 28212658, 2017). "Conversely, loss of DCC expression, a homolog of NEO1, correlates inversely with the degree of NB dissemination, acting in this context as a tumor suppressor." (PMID 28038459, 2017). "The importance simultaneously targeting tumor cells and the tumor microenvironment of urogenital cancers by anti-cancer drugs in is also underscored by results with DCC-2701 as a c-Met/TIE-2/VEGF-R inhibitor." (PMID 28212658, 2017). "DCC (Deleted in Colorectal Carcinoma) was considered as one of the most important tumor suppressors in the early 1990s, but nearly declassified at the end of the same decade, after demonstration of its role in nervous system establishment." (PMID 26882243, 2016).
tumor (continued). "DCC (Deleted in Colorectal Carcinoma) has been demonstrated to constrain tumor progression by inducing apoptosis unless engaged by its ligand netrin‐1." (PMID 26882243, 2016). "Consistent with its tumor suppressor function, downregulation of DCC expression has been demonstrated in a number of cancer types including colorectal, ovarian, pancreatic, hepatocellular carcinomas, and neuroblastoma." (PMID 27096627, 2016). "The deleted in colorectal carcinoma (DCC) is a well familiar tumor suppressor gene that functions in cell migration, cell cycle arrest and apoptosis, and has been found to be frequently deregulated or inactivated in various cancers." (PMID 26891331, 2016). "The well established tumor suppressor function of DCC is a result of its capacity to induce apoptosis as a dependence receptor for netrin-1 in case a ligand-receptor binding is interfered or the ligand is not present." (PMID 27096627, 2016). "LOH for the DCC gene, KRAS gene mutation, and microsatellite instability were also evaluated for each tumor, utilizing standard polymerase chain reaction methods." (PMID 26970738, 2016). "DCC is a single-pass transmembrane protein that belongs to the immunoglobulin superfamily, and it is a candidate tumor suppressor gene located on chromosome 18q21." (PMID 27127179, 2016). "It is possible that RAC1P29S and DCC loss cooperate in a manner similar to that of PTEN loss and mutations in BRAF or RAS in promoting melanoma tumor growth." (PMID 23372575, 2012). "In agreement with expression of other dependent receptors like DCC and UNC5H which have been regarded as tumor suppressors because of their reported loss of function in variety of cancers and pro-apoptotic ability." (PMID 22666451, 2012). "The 9p21.1 locus contains CDKN2A and the 18q21.1 contains DCC, both are well known tumor suppressors." (PMID 18549475, 2008). "A second question is related to netrin-1 expression in human colorectal tumours, as it would be expected that a similar selective advantage for a tumour is either to lose receptor expression (as it occurs for DCC and/or UNC5H) or to gain netrin-1 expression." (PMID 15956977, 2005). "Along this line, in the early 1990s, the DCC gene was proposed as a putative tumour suppressor gene." (PMID 15956977, 2005). "In cancer, deletion of genes coding for DCC and UNC5H would induce loss of the proapoptotic signal, thus providing a selective advantage for tumour escape." (PMID 15956977, 2005). "Tumour suppressor genes such as nm23, DCC and Smad4 have been reported to play a role in liver metastasis." (PMID 12618882, 2003). "Immunohistochemical studies on DCC protein expression of 14 selected tumours correlated well with the RT-PCR-based results." (PMID 9155051, 1997). "Impaired DCC mRNA expression was detected more frequently in grade 3 ovarian epithelial tumours than in grade 1 tumours (P = 0.002)." (PMID 7880725, 1995). "In addition, we have yet to examine the possible roles of other NTN1 receptors in PDAC innervation and development, despite the roles of UNC5B and DCC in neural development, tumor cell growth and EMT." (PMID 40777309, 2025). "Additionally, clinicopathological relevance analyses demonstrated that the risk score was significantly associated with tumor status at follow-up, history of radiotherapy, presence of residual tumor, and DCC histological subtype." (PMID 41008826, 2025). "Notably, DCC-2036 treatment group dramatically prolonged the tumor-free survival of BALB/C-nude mice (2 × 105 group)." (PMID 36042208, 2022). "Additionally, tumor suppression and metastasis suppression have been reported with the restitution of normal DCC function." (PMID 35176183, 2022). "DCC is considered a tumor suppressor; downregulation of TRIM9 and TRIM68 in BC may lead to changes in BC, although we did not see the correlation in the mRNA level (Spearman coefficient r = 0.022, 0.043)." (PMID 35928444, 2022).
tumor (continued). "DCC (Deleted in Colorectal Cancer) encodes the netrin-1 receptor, which acts as a tumor suppressor when not bound to netrin-1, and as an axon guidance when bound to netrin-1." (PMID 35140737, 2021). "This mini-review summarizes recent work on the induction of cancer properties in parallel with the presence of EMT activities in the presence of serine proteases, with the focus on those tumor suppressors known as “dependence” receptors such as neogenin and Deleted in Colorectal Cancer (DCC)." (PMID 32117748, 2020). "Studies in Drosophila have suggested that the DCC gene functions as an invasive tumor suppressor." (PMID 29293529, 2018). "However, netrin-1 shortage induces cleavage of DCC at its intracellular domain and promotes apoptosis; thus, DCC is considered as a tumor suppressor." (PMID 30373548, 2018). "The enzymes deplete cells of tumour suppressors such as deleted in colorectal cancer (DCC) and neogenin, so their potential presence in the food chain might represent an important link between diet and cancer." (PMID 28238104, 2017). "However, DCC has been recently reinstated as a receptor that constrains tumor progression in breast and colorectal cancers, by inducing apoptosis unless engaged by its ligand netrin‐1." (PMID 26882243, 2016). "As such, DCC could act as a conditional tumor suppressor by triggering apoptosis of cells in excess when levels of netrin‐1 are limiting." (PMID 26882243, 2016). "The fact that the DCC gene may be considered a tumour suppressor was confirmed by a study in which the tumour phenotype was reverted by transfection of the DCC gene." (PMID 25932044, 2015). "Here, we test the hypothesis that specific candidate gene methylation markers (CCNA1, NDN, CD1A, DCC, p16, GADD45A) are associated with tumor recurrence and survival, in a well-characterized, prospective, cohort of 346 HNSCC patients." (PMID 26518708, 2015). "It remains to be determined to which extent the frequently observed methylation changes or loss of netrin-1 receptors, among others DCC and members of the UNC5 family, may contribute to the increased malignant potential of tumor cells." (PMID 24647424, 2014). "DCC (Deleted in Colorectal Carcinoma) is an important tumor suppressing gene." (PMID 24565108, 2013). "Such an analysis may provide an effective simulation of human tumors and offer insight into the putative tumor suppressing functions of DCC." (PMID 21672235, 2011). "No mutations of DCC were found in any of the tumours, although 78% (47/60) of the primary tumours showed apparent loss or reduction of DCC expression by immunohistochemistry." (PMID 11461076, 2001). "Three candidate tumour suppressor genes, DCC, SMAD4 and SMAD2, map to this region." (PMID 10993648, 2000). "DCC protein expression was undetectable in eight of the nine tumours missing both wild-type codons." (PMID 9484816, 1998). "In order to identify the possible role of the DCC gene in neoplasms of the human female reproductive tract, messenger RNA expression of the DCC gene was examined by reverse transcriptase-polymerase chain reaction, and expression of the DCC gene product was detected immunohistochemically." (PMID 7880725, 1995). "Additionally, several mutations not previously reported in OSCC sequencing studies were detected in 7% of cases including mutations in ARID1A (chromatin remodeling), BIRC6 (apoptosis inhibition), DCC (neural regulation and tumor suppression), and NCOR1 (transcriptional inhibition)." (PMID 41154345, 2025). "Moreover, STAiRs 1, 2 and 6 may execute specific functions in myeloma tumor integrity, as it was indicated exemplarily by STAiR2 and its ability to inhibit the tumor suppressor function of DCC in INA-6 cells." (PMID 28801664, 2017). "However, recent studies have also challenged this hypothesis and have suggested a role for DCC in suppressing tumor growth and metastasis." (PMID 26207151, 2015). "Interestingly, the hub of the second top-ranked EpiMod was DCC, a putative tumour suppressor." (PMID 24265601, 2013).
tumor (continued). "Finally, our nude mouse model demonstrated that DCC-2036 had a good anti-tumor activity in vivo." (PMID 24009732, 2013). "It was therefore hypothesized that DCC functions as a tumor suppressor." (PMID 21672235, 2011). "However, as discussed in detail in another review, none of these concerns appears sufficient to discard the hypothesis that DCC acts as a tumour suppressor gene." (PMID 15956977, 2005). "Thus, another tumour-suppressor gene, such as DCC, discovered as the first tumour-suppressor candidate in the region may also exist in this chromosome region." (PMID 9820171, 1998). "No allelic losses were detected at other 18q loci in tumours which retained both DCC alleles." (PMID 7917921, 1994). "In contrast to tumors, the adjacent non-tumor tissues harbored eight genes with recurrent HBV integration, including FN1, DCC, OAZ2, ANO3, ENOX1, GRIK4, NPAT, and SNCAIP." (PMID 34209079, 2021). "Based on these data, we conclude that CRC‐associated downregulation of VPS4B does not reflect its own tumor suppressor function but rather represents a passenger alteration co‐existing with concomitant loss of the neighboring 18q‐located tumor suppressors, such as DCC, SMAD2, and SMAD4." (PMID 31930723, 2020). "One possible explanation for this variation is that in many human cancers, up-regulation of Netrin family members inhibits apoptosis that is induced by dependent receptors such as DCC and UNC5H, thus promoting tumor progression." (PMID 32251318, 2020). "Netrin-1 and its receptors, DCC and UNC5H, have been reported to be important factors for tumor development and progression in several tumor entities." (PMID 29854303, 2018). "LOH of DCC, BCL2, and SMAD4 were validated using microsatellite marker quantification between tumor and matched normal samples for each specific locus." (PMID 30219970, 2018). "In a substantial part of human cancers, netrin‐1 (NTN1) is upregulated and this upregulation is inhibiting apoptosis induced by its so‐called dependence receptors, DCC and UNC5H, and thus promotes tumor progression." (PMID 27378792, 2016). "In a number of human cancers, NTN1 upregulation inhibits apoptosis induced by its so‐called dependence receptors DCC and UNC5H, thus promoting tumor progression." (PMID 27378792, 2016). "The methylation statuses of the promoters of 11 tumor-related genes (p16, RASSF1A, E-cadherin, H-cadherin, MGMT, DAPK, DCC, COL1A2, TAC1, SST, and GALR1) were analyzed in 133 HNSCC cases using quantitative methylation-specific PCR." (PMID 27027429, 2016). "Other conditional tumor suppressor genes identified in CRC and other cancers, include DCC, UNC5C, p75NTR and MET." (PMID 23874207, 2013). "Specifically, lower expression of APC, DCC, and DSC2 and higher expression of MACC1 was observed in the tumor samples relative to the paired adjacent normal tissue in both the microarray and qPCR assays." (PMID 22363440, 2012). "Conversely, cluster 4 was mainly characterised by the presence of genes involved in signal transduction and cell structure, including a number of tumour suppressor genes (FAT-2, DCC, RASSF-4 and BRAF) that play a role in the control of cell proliferation." (PMID 20700504, 2010). "Performing QMSP with a panel of three genes (CDKN2A, CCNA1 and DCC), we found 64% of HNSCC tumours were hypermethylation informative." (PMID 18594522, 2008). "Because netrin-1 and its receptors have already been reviewed for their role in neuronal guidance, we will mainly describe here the implications of netrin-1, DCC and UNC5H in apoptosis and consider the consequences on tumour escape mechanisms." (PMID 15956977, 2005).
tumor (continued). "We have shown that many tumour suppressor and tumour-related genes, such as APC, DAP-kinase, DCC, E-cadherin, hMLH1, p16, RASSF1A and RUNX3, exhibit promoter hypermethylation in both neoplastic and non-neoplastic gastric epithelia at variable frequencies." (PMID 15138487, 2004). "Reconstituted expression of DCC in HHUA had little effect on in vitro growth, but suppressed tumour formation in mice completely." (PMID 10646905, 2000). "The functional relevance of chromosome 18 loss has been discussed longish and controversially with involvement of several tumor suppressors like DCC, Elongin A3, SMAD2, SMAD4, and MIR1-2, but so far, no conclusive results exist." (PMID 40410286, 2025). "Their further research demonstrated that the timing of molecular mutations in UNC5C and DCC was not random, with UNC5C inactivation occurring in early tumour lesions and DCC locus changes forming through progressive accumulation." (PMID 38546656, 2024). "The timing of molecular mutations in UNC5C and DCC was not random, with UNC5C inactivation occurring in early tumour lesions and DCC locus changes forming through progressive accumulation." (PMID 38546656, 2024). "Netrins have, however, been found to play a role in tumor biology, where in particular DCC and UNC5 positively regulate apoptosis in the absence of netrin-1 but negatively regulate apoptosis in the presence of netrin-1." (PMID 36499024, 2022). "Similarly, the plasma methylation of SEPT9, DCC, BOLL, and SRFP2 showed stronger correlation with tumor burden than CEA and CA-19-9." (PMID 34208598, 2021). "The resulting topology integrates centrally involved proteins of the common signaling pathways and generally accepted cancer drivers in CRC—such as APC, p53m, KRAS, DCC, TGFβR, PTEN and SMAD4 allowing a simplified view on the progression from normal cells to tumor cells (Table A2, Figure A8)." (PMID 31861874, 2019). "Interestingly, recent studies have demonstrated that DCC as well as UNC5C serve as dependence receptors for netrin-1, thus, reinforcing their potential role as tumor-suppressors in human cancers." (PMID 26207151, 2015). "Two drug candidates, TRAP-netrinDCC and TRAP-netrinUNC5A, which are Fc-fused and stabilized ectodomains of respectively DCC or UNC5A, have been shown to trigger death of netrin-1 expressing tumour cells in vitro and tumour growth inhibition in engrafted mice models (not shown)." (PMID 24293316, 2013). "To further investigate results from unsupervised and supervised analysis of tumor cases we applied the AC1/AC2 gene signature and the DCC classifier to four data sets comprising 360 gene expression profiles of histologically normal bronchial airway epithelial specimens." (PMID 22676229, 2012). "Accumulating evidence implies that this positive signaling pathway is frequently inactivated in human cancers, as it was shown that expression of DCC and UNC5H is lost during tumor progression, thus, conferring a selective advantage to the tumor cell for survival." (PMID 21789787, 2011). "Analysis of methylation status of DCC revealed that methylation frequently occurred in both primary tumours (75%; 45/60) and corresponding non-cancerous gastric mucosae (72%; 43/60)." (PMID 11461076, 2001). "Consequently, targeting the FGR-AKT-SP1-DKK1 pathway with DCC-2036 could potentiate immunotherapy by enhancing CD8+ T cell functionality and their tumor infiltration." (PMID 39788945, 2025). "Hence, we tested whether DCC-3116-mediated inhibition of ULK1/2, starting at tumor initiation in KL mice, would inhibit tumor growth." (PMID 39213022, 2024). "Although DCC-deficient mice (like MET D1374N mice, data not shown) do not develop spontaneous tumors, experiments in which they were crossed with mice bearing a cancer-predisposing APC mutation suggest that DCC acts as a conditional tumor suppressor gene." (PMID 32091387, 2020).